IL17F (interleukin 17F)
Diseases named in the same sentence as IL17F in open-access papers (continued):
Sharing a sentence is not in itself a finding about the gene and the disease.
psoriasis (continued). "Recent clinical studies have shown that therapy with bimekizumab, a dual IL-17A and IL-17F neutralizing antibody, resulted to pronounced clinical responses in patients with psoriasis and psoriatic arthritis." (PMID 39011515, 2024). "In psoriasis treatment, in addition to agents that inhibit IL-17A, agents that inhibit both IL-17A and IL-17F have been used, and both have shown marked efficacy in skin conditions." (PMID 39519167, 2024). "Baseline serum IL-17A, IL-17F, and IL-22 levels were shown to be higher in patients with moderate-to-severe psoriasis than in healthy controls." (PMID 39114670, 2024). "Particularly, among activated T cells, Th1 cells produce IFN-γ, which activates macrophages, and Th17 cells release IL-17A, IL-17E, IL-17F, and IL-22, which play a role in the pathogenesis of psoriasis." (PMID 39765869, 2024). "Experimental and clinical studies suggest that the IL-17F gene locus plays a role as a central cytokine in the immunopathogenesis of psoriasis." (PMID 38331704, 2024). "The Multi-Analyte Flow Assay test showed that IMQ-induced psoriasis in mice had a notable effect on reducing IFN-γ, TNF-α, IL-9, IL-17F, IL-22, and IL-17A psoriasis-related inflammatory cytokines in the APLNs, Cal/Bms, and FA groups." (PMID 39534602, 2024). "T17 cells, which secrete the proinflammatory effector molecules IL-17A and IL-17F, are a significant source of IL-17A in psoriatic skin and play a pivotal role in psoriasis pathogenesis." (PMID 39114670, 2024). "Recent developments include treatments that target both IL-17A and IL-17F in the psoriasis field, though each cytokine’s impact on internal organ damage is still under debate." (PMID 39519167, 2024). "The upregulation of several cytokines and kinases has been implicated in the pathogenesis of psoriasis, including tumor necrosis factor-α (TNF-α), IL-17A, IL-17F, and IL-23." (PMID 39459016, 2024). "While IL-17A is more potent, IL-17F is more abundant in skin lesions of psoriasis (by approximately 30-fold), and can drive inflammation independently of IL-17A." (PMID 39459016, 2024). "Since 2015, biologics targeting IL‐17A, IL‐17F, IL‐17RA, and IL‐23p19 have become available in Japan, thus expanding treatment options for patients with psoriasis." (PMID 39269210, 2024). "These two cytokines have synergistic/cooperative effects on one another, and clinical trial data for bimekizumab, a biologic with dual IL-17A and IL-17F inhibition, has achieved high rates of Psoriasis Area and Severity Index (PASI)-100 clearance." (PMID 38627868, 2024). "In order to better understand the mechanisms by which Clobetasol- and Tacrolimus-mediated signaling repress psoriasis in our model, we examined the mRNA expression of IL-17a and IL-17f that are known potent cytokines in psoriatic plaques." (PMID 39273201, 2024). "This case appears to be the first documented instance of effective anti-IL-17A/IL-17F antibody treatment in a psoriasis patient undergoing HD, with a sustained positive response for eight months." (PMID 38673523, 2024). "The IL-17 cytokine family comprises six isoforms (IL-17A to IL-17F), with IL-17A being the most extensively studied in the context of psoriasis." (PMID 38541607, 2024). "During psoriasis pathogenesis, the epidermal microenvironment is enriched with inflammatory factors such as IL-17A and IL-17F, which can induce the expression of DAMPs in keratinocytes." (PMID 38255845, 2024). "Bimekizumab, which suppresses both interleukin (IL)‐17A and IL‐17F, has recently been approved as a biologic for psoriasis." (PMID 38482898, 2024). "But as IL-17F does not only contribute to psoriasis, but also to mucosal immunity, the blockade of IL-17F along with IL-17A results in an increased risk for candida infections." (PMID 37283755, 2023). "Earlier, IL-23 secreted by these cells was shown to stimulate γδ T cells to secrete IL-17A, IL-17F, and IL-22 in psoriasis." (PMID 36645209, 2023).
psoriasis (continued). "APM gels treated the psoriasis mouse model, and it shows a reduction in the proinflammatory cytokines (IL-8, IL-17A, IL-17F, and IL-23)." (PMID 37896163, 2023). "76.5% of IL17A+ T-cells, 61.4% of IL17F+ T-cells, and 100% of IL17A+IL17F+ T-cells were within the CD161+ T-cell cluster in pretreatment psoriasis lesional skin." (PMID 37781383, 2023). "In this review, we will summarize the current knowledge around IL-17A and its five currently known homologues, namely IL-17B, IL-17C, IL-17D, IL-17E (also known as IL-25) and IL-17F, in relation to skin inflammation in general and psoriasis in particular." (PMID 37283755, 2023). "IL-17F is an IL-17 homologue who’s relevance in the pathogenesis of psoriasis has long been overlooked." (PMID 37283755, 2023). "Th17-derived proinflammatory cytokines (IL-17A, IL-17F, IL-21, IL-22, and IL-26) have a critical role in the pathogenesis of several autoimmune diseases such as psoriasis, multiple sclerosis, rheumatoid arthritis, and inflammatory bowel disease." (PMID 37495626, 2023). "For the T17 axis transcriptome, systemic IL-17A blockade depleted 100% of IL17A+ T-cells and 95% of IL17F+ T-cells in psoriasis skin." (PMID 37781383, 2023). "Subsequently, we will summarize the current knowledge around IL-17A and its five currently known homologues, namely IL-17B, IL-17C, IL-17D, IL-17E (also known as IL-25) and IL-17F, in relation to psoriasis with a focus on the most recent discoveries." (PMID 37283755, 2023). "IL-23, secreted by myeloid dendritic cells (mDCs), is increased when psoriasis persists or worsens and promotes Th17 cells differentiation to produce more IL-17A and IL-17F, which are pathophysiological evidence of psoriasis." (PMID 37298949, 2023). "In particular, the nanobody sonelokimab inhibition of both IL-17A and IL-17F is under clinical study for its efficacy and safety in patients with psoriasis." (PMID 37238999, 2023). "While the contribution of IL-17F in psoriasis is now accepted, its role in psoriatic arthritis remains under debate." (PMID 37283755, 2023). "We suggest that SNP rs763780 in IL-17F, through its effects on IL-17F, has an important role in the pathogenesis of psoriasis." (PMID 37239484, 2023). "Although anti-IL-17A monoclonal antibody does not directly target IL-17F, systemic IL-17A blockade also removed 95% of IL17F-expressing T-cells in psoriasis skin, potentially mediated by IL-23 reduction in dendritic cells." (PMID 37781383, 2023). "Currently, the IL23/Th17 axis plays a crucial role in the occurrence and development of psoriasis, especially due to the IL-17A and IL-17F proinflammatory cytokines, which are among the most often incriminated factors in pathogenesis." (PMID 37239484, 2023). "One of the sources of IL-17A in psoriasis is Th17 cells, then they are stimulated to secrete further cytokines by IL-23, which include (besides IL-17A): IL-17F, IL-21, IL-22, IL-26, and TNF-α." (PMID 36226313, 2022). "There are six known IL-17 family members including IL-17A, IL-17B, IL-17C, IL-17D, IL-17E, and IL-17F, with IL-17A and IL-17F being the best studied in psoriasis." (PMID 35008981, 2022). "Brodalumab, a human monoclonal antibody against IL-17RA, which mediates the downstream signaling of IL-17A, IL-17F, IL-17A/F, IL-17C, and IL-17E, has been approved for the treatment of psoriasis." (PMID 35626662, 2022). "The expression of TNF-α and IL-6 as well as IL-22, IL-23, and IL-17 family of cytokines (IL-17A, IL-17E, and IL-17F) was significantly increased in psoriasis skin lesions." (PMID 35663991, 2022). "This is the first study to address the protein levels of IL-17A, IL-17F and their receptors in the skin of PsA patients with mild psoriasis (mean PASI score < 10) in comparison with HD skin." (PMID 35203534, 2022). "We found that transcription levels of IL17A, IL17C, and IL17F were increased in psoriasis compared with normal skin, which was in parallel with their receptors IL17RA, IL17RC, IL17RD, and IL17RE." (PMID 36009523, 2022).
psoriasis (continued). "The fast response to bimekizumab emphasizes the crucial role of IL-17F in the pathogenesis of psoriasis." (PMID 36614836, 2022). "Even if the actions of IL-17F were neutralized by blocking the IL-17RA receptor with brodalumab, only limited efficacy on his psoriasis was observed." (PMID 36614836, 2022). "When IL-17F was studied in mice models of psoriasis, results showed that IL-17F-producing cells were more abundant than those producing IL-17A and IL-22." (PMID 34201664, 2021). "In psoriasis, IL-17-producing T helper cells (Th17) are central in the pathogenesis and Th17-related cytokines such as IL-17A, IL-17F and IL-22, together with TNFα, drive epidermal hyperplasia." (PMID 34616394, 2021). "It is well-known that IL-17 cytokine family (produced by Th17 cells) is involved in inflammatory autoimmune-mediated diseases such as psoriasis, where tissue inflammation also occurs due to high expression of IL-17A and IL-17F." (PMID 34947847, 2021). "Nonetheless, the relevance of IL-17F in psoriasis pathogenesis has been shown in patients and animal models." (PMID 34778294, 2021). "Canonical pathway analysis showed the role of IL17A in psoriasis, the role of IL17F in inflammation in airways, and chronic obstructive pulmonary disease (COPD) signaling pathways were severely affected by SARS-CoV-2 infection." (PMID 34582497, 2021). "The feature that broadly blocks IL-17A, IL-17F, IL-17C and IL-17E enables IL-17RA to rapidly improve the clinical and histological features of psoriasis." (PMID 34975883, 2021). "Our group has shown that IL-15 and IL-23 act synergistically on cocultures of CLA+ memory T cells and autologous epidermal cells to produce significantly increased levels of IL-17F and IL-17A in psoriasis when compared to CLA− T cells cocultures." (PMID 34778294, 2021). "Plaque and guttate psoriasis patients showed significant CLA+ T cells-dependent CA-mediated induction of IL-17F, IL17A, and IL-9 compared to unstimulated CLA+T/EPI and CA-stimulated CLA−T/EPI cocultures." (PMID 33546306, 2021). "A preferential CLA+ T cell response to Candida albicans, dominated by IL-17F, was found in psoriasis but also in control subjects." (PMID 33546306, 2021). "We chose stimuli known to be relevant in the pathogenesis of psoriasis like IL-17A, IL-17F, TNFα, IL-1α, flagellin as well as murine S100A8 as endogenous Toll-like receptor (TLR)-trigger." (PMID 33643287, 2020). "Secondly, quantification of local and systemic levels of both IL-17 cytokines in patients with psoriasis, psoriatic arthritis, and ankylosing spondylitis revealed a greater abundance of IL-17F relative to IL-17A (>30-fold)." (PMID 32973785, 2020). "Recent clinical studies have shown that dual IL‐17A and IL‐17F blockade by bimekizumab results in rapid and profound efficacy in the treatment of PsA 20 and psoriasis." (PMID 31850514, 2020). "Although IL-17A is known to be the more potent of the two cytokines, IL-17F is the more abundantly expressed of the two in psoriasis and spondyloarthritis." (PMID 32973785, 2020). "In two patients with difficult-to-treat types of psoriasis, we observed both IL-17A and IL-17F-producing KLRB1+ cells." (PMID 33329560, 2020). "detected levels of IL‐17F and IL‐17A in the serum of PsA, AS, and psoriasis patients using a highly sensitive Singulex immunoassay." (PMID 31850514, 2020). "Compared with healthy controls, the skin of patients with psoriasis has been shown to contain increased levels of Th17 cells with IL-17A, IL-17F, and IL-22 proteins being abundantly produced." (PMID 32392785, 2020). "High abundance of these S100-proteins during psoriasis can be explained especially by the effects of IL-17A, IL-17F, TNF, and IL-1α on S100A8/S100A9 expression, which are all central players in the pathogenesis of psoriasis." (PMID 33643287, 2020).
psoriasis (continued). "With promising early clinical data in psoriasis, psoriatic arthritis, and ankylosing spondylitis, dual inhibition of IL-17A and IL-17F with bimekizumab offers a new therapeutic approach for the treatment of patients with immune-mediated inflammatory diseases." (PMID 32973785, 2020). "IL-17A, and its structurally similar family member IL-17F, have been shown to be functionally dysregulated in certain human immune-mediated inflammatory diseases such as psoriasis, psoriatic arthritis, and axial spondyloarthritis." (PMID 32973785, 2020). "More recently, bimekizumab, a monoclonal antibody targeting IL-17A and IL-17F, demonstrated high efficacy in psoriasis." (PMID 30109481, 2018). "In the IL-23/Th17 axis model of psoriasis, IL-23 is able to produce and induce Th17 cell lymphocyte activation, which subsequently releases IL-17A, IL-17C, IL-17F, IL-22 and other related pro-inflammatory cytokines." (PMID 30544700, 2018). "IL-17A has been well characterized as one of the major drivers for psoriasis pathogenesis whereas IL-17F shares some redundant functions to IL-17A but its role in psoriasis is less defined." (PMID 30185226, 2018). "Top up-regulated DEGs in CP vs C include previously identified psoriasis-associated genes such as IL36A/G, SPRR2A/B/F, SERPINB4, S100A7A, S100A9, and IL17F while top down-regulated DEGs include SERTM1, IL6, and ADAMTS16." (PMID 30054515, 2018). "Inhibition of IL-17A, IL-17 receptor A, or simultaneous inhibition of IL-17A and IL-17F leads to disruption of signaling pathways critical to the development and maintenance of psoriasis." (PMID 30109481, 2018). "IL-17A and IL-17F production is probably the most relevant effect of S. pyogenes on CLA+ T cells in psoriasis." (PMID 30013558, 2018). "In summary, the observations made to date suggest that circulating CLA+ T cells in psoriasis patients produce increased amounts of IL-17A, IL-17F, and IL-9, in comparison to healthy controls, when activated by S. pyogenes." (PMID 30013558, 2018). "IL-22 and IL-17F cellular sources in psoriasis have been less studied and possibly assumed to be closely co-regulated with IL-17A." (PMID 28790368, 2017). "Gene expression profiles of the lesional psoriasis have established that psoriasis is mainly induced by IL-23 and type 17 (IL-17A, IL-17F, and IL-22) cytokines." (PMID 29295520, 2017). "In B6 mice, IMQ increased expression of Il17a, Il17b, Il17c, and Il17f, partially consistent with human psoriasis, but in the BALB/c strain such genes were unaltered by IMQ." (PMID 28279190, 2017). "An important cytokine that is generated by Th17 cells, IL-17F, shows significantly higher mRNA expression in lesional skin, and serum levels of the IL-17F protein were substantially increased in a psoriasis(-like) mouse model as well." (PMID 27274756, 2016). "Although the pathogenesis of psoriasis is not fully understood, evidence suggests that many cytokines, including IL-6, IL-17A, IL17F, IL-22, IL-23 and TNF-α, are involved and interact as a network in the pathogenesis of psoriasis." (PMID 27581210, 2016). "Nonetheless, the peak ratios are observed for the Role of Il17F in inflammatory diseases and the role of Il17A in psoriasis." (PMID 26932723, 2016). "Th17 cells synthesize IL-17A, IL-17F, IL-21, and so forth and have been demonstrated in autoimmune disease such as Sjögren's syndrome, multiple sclerosis, psoriasis, autoimmune uveitis, juvenile diabetes, rheumatoid arthritis, and Crohn's disease." (PMID 26078981, 2015). "Of particular interest are cytokines involved in Th1 and Th17 biology (IL-12, IFNg, IL-23, IL-17A and IL-17F), which have been shown to play a role in psoriasis." (PMID 23308107, 2013). "It is on that basis, we discovered that curcumin can suppress inflammation in IMQ-induced psoriasis-like mice model and decrease the cytokines production, such as IL-17A, IL-17F, IL-22, IL-1β and TNF-α." (PMID 23825622, 2013).
psoriasis (continued). "Additionally, γδ T cells contribute to psoriasis by secreting pro-inflammatory cytokines such as IL-17A, IL-17F, and IL-22, promoting inflammation and keratinocytes proliferation." (PMID 40406126, 2025). "However, in diseases linked to MHC-I genes, including psoriasis, PsA, and axSpA, it is likely that tissue-resident memory (TRM) CD8+ T cells are key producers of both IL-17A and IL-17F; future studies should aim to address this." (PMID 41322402, 2025). "Whilst the head-to-head data in psoriasis has established superior efficacy of dual IL-17A and IL-17F in the skin compared to other biologic disease modifying anti-rheumatic drugs (bDMARDS) such as adalimumab and secukinumab, similar efficacy was observed at the joint compared to anti-TNF." (PMID 41322402, 2025). "In addition to targeting IL-17A, newly available simultaneous targeting of IL-17F appears to show enhanced efficacy compared to inhibition of IL-17A alone in psoriasis." (PMID 41322402, 2025). "IL-17-A, IL-17F, and IL-17-A/F are primarily involved in the development of psoriasis." (PMID 40243580, 2025). "IL-17A, IL-17F, and IL-22 are elevated in the sera and/or skin lesions of patients with psoriasis." (PMID 39114670, 2024). "This situation has once again highlighted the critical role of IL-17F in psoriasis pathogenesis." (PMID 38331704, 2024). "Based on the central role of IL-17F in the pathogenesis of psoriasis, the authors thought that variations in this gene could affect the susceptibility and severity of this disease." (PMID 38331704, 2024). "Moreover, ILC3s have also been demonstrated to elicit psoriasis-like symptoms in mice by secreting IL-17A, IL-17F, and IL-22." (PMID 38255845, 2024). "In May 2022, bimekizumab, a humanized monoclonal antibody that binds both IL‐17A and IL‐17F, was approved in Japan for the treatment of patients with moderate‐to‐severe psoriasis aged ≥15 years." (PMID 38482898, 2024). "Baseline substudy serum samples from patients with psoriasis (n = 118) contained significantly (all P < .01) higher concentrations of IL-17A, IL-17F, IL-22, IL-8, CCL22/macrophage-derived chemokine (MDC), and CCL4/MIP-1β than an independent, healthy control serum cohort (n = 25)." (PMID 39114670, 2024). "The role of IL-17A and IL-17F has been established in chronic immune-mediated inflammatory diseases (IMIDs), such as psoriasis (PsO), psoriatic arthritis (PsA), axial spondylarthritis (axSpA), hidradenitis suppurativa (HS), inflammatory bowel disease (IBD), multiple sclerosis (MS), and asthma." (PMID 37600764, 2023). "Furthermore, treatment with Treg‐of‐B‐induced M2 macrophages in psoriasis resulted in a reduction in local inflammation, including decreased skin Il17f, Il23 and Tnfα expression, immune cell infiltration and skin epidermal thickness." (PMID 37073709, 2023). "Moreover, IL-23 secreted by dendritic cells and macrophages stimulate γδ T cells to secrete IL-17A, IL-17F, and IL-22 in psoriasis." (PMID 36645209, 2023). "Importantly, therapeutic inhibition of aberrant IL-17A and IL-17F activities is used as treatment for skin diseases such as psoriasis and other autoimmune conditions." (PMID 37291218, 2023). "Furthermore, tapinarof exhibits direct binding to the aryl hydrocarbon receptor (AhR), leading to a reduction in the production of inflammatory cytokines, including IL-17A, IL-17F, IL-22, IL-23, and IL-1β, as demonstrated in a psoriasis-like mouse model." (PMID 38288335, 2023). "IL-17A and IL-17F levels were associated with baseline PASI score and psoriasis BSA." (PMID 37587493, 2023). "In addition, the extracellular vesicles of Staphylococcus epidermidis ameliorate IMQ-induced psoriasis by reducing the number of Gr1-positive cells infiltrating the skin and IL-17F expression." (PMID 37964882, 2023). "Furthermore, psoriasis-related factors, such as IL-17A, IL-17F, IL-22, and IL-23R, can be transcriptionally activated by STAT3, suggesting that STAT3 plays a promoting role in psoriasis development." (PMID 36835162, 2023).